OPA1 (OPA1 mitochondrial dynamin like GTPase)
Diseases named in the same sentence as OPA1 in open-access papers (continued):
Sharing a sentence is not in itself a finding about the gene and the disease.
autosomal dominant optic atrophy (continued). "Mutations in some mitochondrial genes have been demonstrated to be the main causes of these metabolic diseases, such as Charcot–Marie–Tooth disease (Mfn2 mutation) and dominant optic atrophy (Opa1 mutation)." (PMID 31551926, 2019). "The most common forms of inherited optic neuropathies, described so far, are the Leber's optic neuropathy (LHON), and the dominant optic atrophy (DOA) caused by mutations in the nuclear gene OPA1." (PMID 31318166, 2019). "OPA1, a dynamin-related GTPase, is involved in the fusion of the outer and inner mitochondrial membranes, and gene mutations are associated with the autosomal dominant optic atrophy (ADOA)." (PMID 31096646, 2019). "OPA1 mutations have previously been discussed in the literature in association with autosomal dominant optic atrophy (DOA), the most common inherited form of optic nerve visual loss." (PMID 31083577, 2019). "The two most common forms of inherited optic neuropathy are autosomal dominant optic atrophy (DOA) secondary to pathogenic variants within OPA1 (OMIM: 165500), and maternally inherited Leber hereditary optic neuropathy (LHON) (OMIM: 535000)." (PMID 31765440, 2019). "The dysfunction of OPA1 is associated with dominant optic atrophy (DOA), which is an optic neuropathy caused by the degeneration of retinal ganglion cells." (PMID 31027297, 2019). "A key molecule for IMM fusion is Optic Atrophy 1 (OPA1, Mgm1 in yeast), a three-membrane-pass protein that faces the intermembrane space and is mutated in autosomal dominant optic atrophy." (PMID 28779209, 2018). "Of note, germline mutations in Mfn2 cause Charcot–Marie–Tooth hereditary-like neuropathy type 2A (CMT2A), while germline mutations in OPA1 causes the autosomal dominant optic atrophy (ADOA) which is the most common genetic cause of optic atrophy in humans." (PMID 29503614, 2018). "As demonstrated by its role as the underlying mechanism of dominant optic atrophy, OPA1 is a crucial mediator of bioenergetic-linked mitochondrial dynamics." (PMID 30249006, 2018). "The importance of mitochondrial fusion to human health is underscored by the findings that mutations in the mitochondrial fusion machinery components Mfn2 and OPA1 cause Charcot-Marie-Tooth disease type 2A and autosomal dominant optic atrophy, respectively." (PMID 28924745, 2018). "Heterozygous mutations in OPA1 are a common cause of autosomal dominant optic atrophy, sometimes associated with extra-ocular manifestations." (PMID 28494813, 2017). "The eat-3 ortholog OPA1 is well known for its association with dominant optic atrophy, an inherited condition characterized by retinal ganglion cell degeneration." (PMID 28539870, 2017). "Mutations in the OPA1 gene are the most common cause of dominant optic atrophy, an optic neuropathy, while polymorphisms in OPA1 are associated with hypertension." (PMID 28513539, 2017). "Dominant mutations of OPA1 cause Autosomal Dominant Optic Atrophy (ADOA), affecting mitochondrial morphology (aggregated and fragmented) and content (reduced content of mitochondrial DNA (mtDNA) and reduced ATP production)." (PMID 28376083, 2017). "Pathogenic mutations in the OPA1 gene have largely been associated with autosomal dominant optic atrophy (ADOA; OMIM#165500), a visual disorder associated with degeneration of retinal ganglion cells." (PMID 28494813, 2017). "Mutations in the opa1 (optic atrophy 1) gene lead to autosomal dominant optic atrophy (ADOA), a hereditary eye disease." (PMID 27468686, 2016). "While mutations in the OPA1 gene induce autosomal dominant optic atrophy (ADOA), this protein also regulates apoptosis and takes part in mtDNA maintenance." (PMID 27573305, 2016). "Mutations in two mitochondrial fusion genes (MFN2 and OPA1) cause neurodegenerative diseases, namely Charcot-Marie Tooth type 2A and autosomal dominant optic atrophy (ADOA)." (PMID 26113818, 2015).
autosomal dominant optic atrophy (continued). "Dominant optic atrophy usually affects both males and females in young childhood, and in the large majority of cases, is due to mutations in the OPA1 gene." (PMID 25132831, 2014). "OPA1, the mammalian homologue of yeast Mgm1p, is a dynamin-related GTPase that was first discovered from a gene mutation causing autosomal dominant optic atrophy." (PMID 22806564, 2013). "An expanding number of degenerative disorders are associated with mutations in the genes encoding MFN2 and OPA1, including Charcot-Marie-Tooth disease type 2A and autosomal dominant optic atrophy." (PMID 23781337, 2013). "OPA1, mutated in dominant optic atrophy, is a multifaceted mitochondria-shaping protein that has genetically distinguishable functions in apoptosis and in mitochondrial fusion." (PMID 22579715, 2012). "The maculopapillary bundle is recognized to be more susceptible to certain metabolic conditions (such as methyl alcohol toxicity) and genetic defects (such OPA1 mutations in dominant optic atrophy) that impair mitochondrial function." (PMID 23049825, 2012). "Mutations in OPA1 are associated with dominant optic atrophy characterized by the progressive loss of retinal ganglion cells, highlighting the importance of OPA1 function in neurons." (PMID 23144624, 2012). "Mutations in the dynamin-like GTPases MFN2 and OPA1, which mediate mitochondrial membrane fusion, cause neurodegeneration in Charcot-Marie-Tooth disease type 2A and autosomal dominant optic atrophy, respectively." (PMID 23144624, 2012). "OPA1, the gene responsible for autosomal dominant optic atrophy (ADOA), represents a good candidate genetic risk factor for POAG, as the clinical phenotypes between ADOA and POAG are similar, and OPA1 is expressed in the retinal ganglion cells and optic nerve." (PMID 22879959, 2012). "In human, mutations of OPA1 cause dominant optic atrophy (DOA), the most common form of autosomal inherited optic neuropathy." (PMID 19221591, 2009). "Most of these genes were investigated only in single studies whereas the OPA1 gene, which is linked to autosomal dominant optic atrophy, has been subject of multiple studies." (PMID 19754948, 2009). "Of particular interest, mutations in OPA1 are linked with neurodegenerative diseases in human and can cause autosomal dominant optic atrophy (ADOA), the most common form of hereditary optic neuropathy." (PMID 19122832, 2008). "Its interest as a possible candidate gene involved in ocular function stems from its relationship with OPA1, a dynamin-related protein of the inner membrane which is mutated in autosomal dominant optic atrophy." (PMID 18846214, 2008). "OPA1 variants are known to cause the autosomal dominant optic atrophy (OPA1; OMIM #165500), which is characterized by progressive bilateral vision loss with onset during the first decade of life, central visual field defects, color vision disturbances, and optic disc pallor." (PMID 39202332, 2024). "Additionally, the loss of PHB2 impairs the stability of Optic Atrophy 1 (OPA1), and mutations in OPA1 have been shown to be associated with dominant optic atrophy, characterized by a gradual loss of retinal ganglion cells." (PMID 39507806, 2024). "Likewise, mutations in Opa1, usually associated with autosomal dominant optic atrophy, have been linked to altered mitophagy and parkinsonism." (PMID 38627765, 2024). "Mutations in OPA1 cause autosomal dominant optic atrophy (ADOA), a leading cause of blindness." (PMID 39616197, 2024). "The importance of OPA1 in the maintenance of mitochondrial structure, genome, and function is further evident from mouse and patient models where mutation or loss of OPA1 gives rise to several pathophysiological outcomes including wasting of skeletal muscle and autosomal dominant optic atrophy." (PMID 39516459, 2024). "Loss-of-function OPA1 mutants cause another neurological condition, dominant optic atrophy (DOA)." (PMID 37190097, 2023).
autosomal dominant optic atrophy (continued). "In addition, the most common cause of autosomal dominant optic atrophy is OPA1, which was included on all three panels." (PMID 36981008, 2023). "Among the fission/fusion proteins, levels of OPA1—the inner mitochondrial membrane-localized protein involved in mitochondrial structure and dynamics—were decreased in GCD2 corneal fibroblasts; OPA1 mutations cause dominant optic atrophy and optic nerve degeneration in retinal ganglion cells." (PMID 36980838, 2023). "Several OPA1 mutations are known to cause autosomal dominant optic atrophy." (PMID 36980838, 2023). "Mutations in OPA1 cause dominant optic atrophy a disease affecting retinal ganglion cells." (PMID 36158192, 2022). "Patients with mutated OPA1 can develop autosomal dominant optic atrophy (ADOA)." (PMID 36081497, 2022). "Interestingly, mutations of OPA1, which result in a loss of inner mitochondrial membrane fusion, lead to an autosomal dominant optic atrophy (from which OPA1 derives its name) and childhood blindness." (PMID 35663397, 2022). "Mutations in the OPA1 gene might cause a lower visual function, which is associated with a lower quality of life and visual ability in patients with autosomal dominant optic atrophy." (PMID 35146926, 2022). "Monoallelic pathogenic variants in OPA1 are associated with autosomal dominant optic atrophy, which could be isolated or associated with other symptoms “Optic atrophy ‘plus’ phenotype”." (PMID 35736332, 2022). "Indeed, levels of aspartate are reduced in Opa1-deficient neurons and in plasma of patients with autosomal dominant optic atrophy caused by OPA1 mutations." (PMID 33649469, 2021). "Genetic disorders of mitochondrial dynamics comprise defects of mitochondrial fusion triggered by mutations in MFN2 or OPA1, exhibiting as Charcot–Marie–Tooth type 2A and autosomal dominant optic atrophy, respectively, and impaired mitochondrial fission caused by mutations in DRP1 and MFF." (PMID 33187380, 2020). "Interestingly, we found similar decreased concentrations of hypoxanthine and xanthine in the plasma of patients with Dominant Optic Atrophy related to OPA1 mutations." (PMID 32012845, 2020). "Similarly, mutation in OPA1 causes derangement in cristae morphology and mitochondrial oxidative capacity and has been associated with the autosomal dominant optic atrophy and Charcot-Marie-Tooth disease type 2A." (PMID 31163678, 2019). "Mitofusins 1 and 2 are required for outer membrane fusion, with fusion of the inner membrane accomplished by optic atrophy-1 (OPA1), which was identified as a causative gene in dominant optic atrophy, and subsequently shown to play a vital role in mitochondrial dynamics." (PMID 30249006, 2018). "The two classical paradigms are Leber hereditary optic neuropathy (LHON), which is a primary mtDNA disorder, and autosomal dominant optic atrophy (DOA) secondary to pathogenic mutations within the nuclear gene OPA1 that encodes for a mitochondrial inner membrane protein." (PMID 27696015, 2016). "Dominant Optic Atrophy is among the most frequent mitochondrial disorder and probably the most frequent form of inherited optic neuropathy and essentially associated to an OPA1 mutation." (PMID 26539208, 2015). "Dominant optic atrophy, in about 70% of cases, is due to mutations in the OPA1 gene." (PMID 25132831, 2014). "For example, mutations in the OPA1 gene cause autosomal dominant optic atrophy." (PMID 24709813, 2014). "OPA1 mutations in humans lead to autosomal dominant optic atrophy." (PMID 23516612, 2013). "Opa1 mutations are responsible for the autosomal dominant optic atrophy (ADOA)." (PMID 22792111, 2012). "Investigation of the OPA1 mutation spectrum in autosomal dominant optic atrophy (ADOA) in Denmark." (PMID 22857269, 2012). "To address our hypothesis that loss of fusion proteins contributes to the development of cardiomyopathy, we studied mice with an OPA1 mutation, modeling dominant optic atrophy." (PMID 23316298, 2012).
autosomal dominant optic atrophy (continued). "Furthermore, in humans, impaired mitochondrial fusion caused by mutations in Opa1 and Mfn2 are associated with dominant optic atrophy or Charcot-Marie-Tooth disease 2A (CMT2A), respectively." (PMID 23285122, 2012). "One of them, dominant optic atrophy (DOA) can be caused by mutations of the OPA-1 gene, coding for a dynamin-related GTPase, which is essential for structural features of the inner mitochondrial membrane (christae) and is required to maintain the ability of mitochondria to fuse with each other." (PMID 21886454, 2011). "Mutations in OPA1, which is involved in various processes related to mitochondrial inner membrane structural dynamics, are linked with neurodegenerative disease in humans and cause autosomal dominant optic atrophy, a common form of hereditary optic neuropathy." (PMID 20664796, 2010). "Mutations of OPA1 result in autosomal dominant optic atrophy (DOA)." (PMID 19718456, 2009). "Mutations in the OPA1 gene are a frequent cause of autosomal dominant optic atrophy." (PMID 19754948, 2009). "Mutations in OPA1 are associated with autosomal dominant optic atrophy (ADOA), the most common mitochondrial optic neuropathy, characterized by retinal ganglion cell degeneration and progressive vision loss." (PMID 40149969, 2025). "Autosomal dominant optic atrophy (ADOA) caused by mutations in the nuclear-encoded OPA1 gene result in the preferential loss of retinal ganglion cells (RGCs) and progressive optic nerve degeneration." (PMID 40447565, 2025). "Mutations in the nuclear-encoded OPA1 gene are the most common cause of autosomal dominant optic atrophy (ADOA), a major cause of inherited visual failure." (PMID 41517394, 2025). "Specifically, MFN2 mutations are linked to Charcot-Marie-Tooth disease (CMT) and OPA1 mutations are associated with autosomal dominant optic atrophy (ADOA)." (PMID 41146909, 2025). "Monoallelic mutations in OPA1, have been recognized as the major cause of the autosomal dominant optic atrophy (DOA) (DOA, MIM#165500), in most cases manifesting with an isolated optic atrophy." (PMID 39233737, 2024). "OPA1 mutations lead to Autosomal Dominant Optic Atrophy (ADOA, MIM 165500), a disease that causes progressive loss of retinal ganglion cells resulting in optic nerve degeneration and blindness." (PMID 39616197, 2024). "OPA1 mutations cause autosomal dominant optic atrophy (ADOA) in humans, which is associated with the selective loss of retinal ganglion cells and blindness." (PMID 39093974, 2024). "OPA1 mutations are associated with autosomal dominant optic atrophy (ADOA; OMIM: 165500), and are the major cause of ADAO." (PMID 36980294, 2023). "Mutations in OPA1 are primarily associated with autosomal dominant optic atrophy (ADOA), a neurodegenerative disorder characterized by vision loss." (PMID 37685840, 2023). "Mutations in the OPA1 gene are found in 32–90% of patients with autosomal dominant optic atrophy (ADOA)." (PMID 37627290, 2023). "Gene mutations necessary for mitochondrial fusion, such as OPA1 or Mfn2, can affect multiple tissues, leading to diseases such as autosomal dominant optic atrophy (DOA) and Charot-Marie-Tooth type 2A (CMT2A) respectively." (PMID 35501558, 2022). "ADOA represents autosomal dominant optic atrophy, and 57 ~ 89% of ADOA cases are caused by variants in the OPA1 gene." (PMID 35883160, 2022). "Some research shows heterozygous OPA1 mutations both on the GTPase or GED domains lead to a decrease of protein quantity and mice of Opa1 heterozygous mutations have become autosomal dominant optic atrophy (DOA) models." (PMID 36578825, 2022). "Autosomal Dominant Optic Atrophy (ADOA) is an ophthalmological condition associated primarily with mutations in the OPA1 gene." (PMID 33927681, 2021). "In this patient, a heterozygous variant (c.1608+622A>G) was found in intron 16 of OPA1, mutations in which lead to autosomal dominant optic atrophy (ADOA)." (PMID 33737949, 2021).
autosomal dominant optic atrophy (continued). "Additionally, an atypical natural history of dominant optic atrophy was recently described in a patient with late onset (62 years) retinal degeneration characterized by acute loss of vision and associated with a dominant mutation in OPA1." (PMID 34209753, 2021). "Autosomal Dominant Optic Atrophy (ADOA), a disease that causes blindness and other neurological disorders, is linked to OPA1 mutations." (PMID 35047497, 2021). "Autosomal dominant optic atrophy (ADOA) is frequently caused by mutations in the optic atrophy 1 (OPA1) gene, with haploinsufficiency being the major genetic pathomechanism." (PMID 34853716, 2021). "Mutations in OPA1 cause autosomal dominant optic atrophy (DOA) as well as DOA+, a phenotype characterized by more severe neurological deficits." (PMID 34014035, 2021). "Opa1 deletion produces mitochondrial fragmentation and causes the Autosomal Dominant Optic Atrophy (ADOA) mitochondrial disease." (PMID 34922554, 2021). "Pathogenic mutations in OPA1 trigger Autosomal Dominant Optic Atrophy (ADOA, MIM#165500) which causes blindness due to Retinal Ganglion Cells (RGCs) death." (PMID 35047497, 2021). "Mutation in the OPA1 gene has been observed to cause autosomal dominant optic atrophy (ADOA) often accompanied by myopathy and progressive ataxia." (PMID 32373609, 2020). "Mutations in OPA1 cause Autosomal Dominant Optic Atrophy (ADOA) characterized by optic nerve atrophy leading to progressive loss of vision." (PMID 31484398, 2019). "Patients with mutated OPA1 can develop autosomal dominant optic atrophy (ADOA), which leads to loss of bilateral visual function within the first two decades of life, or may present with additional signs of peripheral neuropathy, deafness, cerebellar ataxia, paraparesis, and myopathy." (PMID 30054480, 2018). "Compensation for impaired oxidative phosphorylation in OPA1-linked autosomal dominant optic atrophy (ADOA) patients has been associated with preservation of vision." (PMID 28424571, 2017). "Autosomal dominant optic atrophy (DOA) is the commonest autosomal form of mitochondrial optic neuropathy, with most patients harboring pathogenic mutations in the optic atrophy 1 (OPA1) gene." (PMID 27974645, 2017). "Progressive retinal ganglion cell (RGC) loss is the pathological hallmark of autosomal dominant optic atrophy (DOA) caused by pathogenic OPA1 mutations." (PMID 28125838, 2017). "Mutations in OPA1 are associated with autosomal dominant optic atrophy (ADOA) in humans, a disease characterized by progressive loss of visual acuity, desensitization of central visual field, optic nerve pallor, and eventual blindness." (PMID 23516612, 2013). "Autosomal dominant optic atrophy (ADOA) is a slowly progressive optic neuropathy that has been associated with mutations of the OPA1 gene." (PMID 23409176, 2013). "Interestingly, mutations in fusion components are linked to neurodegenerative disorders with Opa1 mutations causative for dominant optic atrophy and mutations in Mfn2 linked to Charcot-Marie-Tooth type 2A disease, a peripheral neuropathy sometimes accompanied by optic degeneration and hearing loss." (PMID 23285122, 2012). "Mutations in Mfn2 cause the Charcot-Marie-Tooth type 2A (CMT2A), one of the most common hereditary neuropathies, and mutations in OPA1 are the predominant cause of autosomal dominant optic atrophy (DOA), a heritable form of optic neuropathy." (PMID 22848813, 2012). "Autosomal dominant optic atrophy (ADOA) is the most common form of hereditary optic neuropathy caused by mutations in the optic atrophy 1 (OPA1) gene." (PMID 20157369, 2010). "Optic atrophy 1 (OPA1) is a dynamin-like GTPase located in the inner mitochondrial membrane and mutations in OPA1 are associated with autosomal dominant optic atrophy (DOA)." (PMID 19221591, 2009).